IL1B (interleukin 1 beta)
Diseases named in the same sentence as IL1B in open-access papers (continued):
Sharing a sentence is not in itself a finding about the gene and the disease.
Miscarriage (continued). "We showed a positive correlation of Il-4 with both INF-γ as well as with Il-1β and TNF-α in the case of miscarriage." (PMID 34444287, 2021). "Th1 cytokine levels in women with miscarriage compared to the control group reached slightly higher values for INF-γ, Il-1β and slightly lower for Il-6 and TNF-α." (PMID 34444287, 2021). "In conclusion, we have found plasma concentrations of the cytokines IL-1β, IL-6 and IL-10, and the chemokines, CXCL8, CCL2, CCL5, CCL7, CX3CL1 cannot predict subsequent miscarriage." (PMID 24699265, 2014). "In contrast, GRP124 with siRNA invalidated the GRP124-regulated expression of NLRP3, IL-18, and IL-1β in human decidual endometrial stromal cells, indicating that the effects of GRP124 on spontaneous miscarriage are through the expression of inflammasome NLRP3, IL-18, and IL-1β." (PMID 35745744, 2022). "Other reports have noted low and non-detectable circulating levels of several cytokines including IL-1β, IL-6, IFN-γ and TNF-α and lack of consistent associations with miscarriage risk." (PMID 24699265, 2014). "MDC1 from miscarriage patients had a significant reduced capacity to secrete IL-1β, IL-6, IL-10, and TNF, while MDC2 from miscarriage patients did not behave differentially from MDC2 of normal pregnant women." (PMID 31681319, 2019).
pneumonitis (17 papers, 2010 to 2025). An inflammatory process affecting the lung parenchyma. "The observed inflammatory changes were accompanied by an increase in cytokines, such as IL-1β and IL-6, as is observed in pneumonitis, which are associated with impaired lung function." (PMID 27144583, 2016). "Moreover, drug-induced pneumonitis has been particularly implicated in the inflammasome-mediated IL-1β and IL-18 production." (PMID 33414419, 2021). "Our data demonstrated that HS diet enhanced pneumonitis and enhanced inflammatory cytokine (IFNγ and IL-1β) expression in CD4+T cells in sites distal to tumor such as lung and also peripheral circulation." (PMID 35741331, 2022). "IL-1β and TNF-α are produced by activated macrophages and are associated with airway hyper-responsiveness and pneumonitis." (PMID 33616187, 2021). "SsRNA stimulation of human leukocytes induced cytokines/chemokines similar to those observed in murine SARS-CoV pneumonitis including IL-1α, IL-1β, IL-6, TNF, CXCL8 (IL-8), CCL2 (MCP-1), CCL3 (MIP-1α), and CCL4 (MIP-1β)." (PMID 23236475, 2012). "BAL myeloid immune populations displayed enhanced expression of IL-1β and decreased expression of counterregulatory interleukin-1 receptor antagonist in patients with ICI-pneumonitis." (PMID 39247203, 2024). "Cytokines such as IL-1α, IL-1β, IL-6, and TNF-α are produced in excess and potentiate pathological processes such as pneumonitis and vascular thrombosis." (PMID 35991665, 2022). "It has been reported that lung tissues of patients with pneumonitis exhibited increased production of pro-inflammatory cytokines, such as TNF-α, IL-1β, and IL-1813,14." (PMID 33414419, 2021).
psoriatic arthritis (17 papers, 2005 to 2026). Joint inflammation associated with psoriasis. "Genetic polymorphisms in the IL-1β locus have been associated with increased susceptibility to the development of psoriatic arthritis, further supporting a direct pathogenetic role." (PMID 41009491, 2025). "Interleukin-17 and IL-12 along with the TH1 cytokines (TNF-α, IL-1B, and IL-10) have been found in higher levels in psoriatic arthritis synovium and IL-17 and IL-23 have been implicated in the potentiation of osteoclastogenesis and bone erosion in psoriatic arthritis joints." (PMID 23209897, 2012). "Ninety pediatric participants (JIA, CD, psoriatic arthritis, healthy controls) underwent serum cytokine profiling (IL-1α, IL-1β, IL-36α, IL-37, IL-6, IL-18, IL-27, IL-31) at baseline and 12 months." (PMID 42196228, 2026). "Recent studies have shown that IL-1β gene expression is significantly increased in patients with psoriatic arthritis compared to both healthy subjects and patients with cutaneous psoriasis alone." (PMID 41009491, 2025). "This suggests that IL-1β is probably involved in the transition from cutaneous psoriasis to psoriatic arthritis and also in the severity of joint inflammation." (PMID 41009491, 2025). "For example, TNFα-, IL-6R- and IL-1β-neutralizing bDMARDs work in RA, whereas IL-17A and IL-12/23-neutralizing bDMARDs are very efficient in psoriatic arthritis or spondyloarthritis." (PMID 34680530, 2021). "The pathogenesis of psoriatic arthritis is related to the innate and adaptive immune response involving different proinflammatory cytokine, including TNF, IL-1β, IL-6, IL-22, IL-23, IL-17A, and IL-18." (PMID 36297574, 2022).
renal cell carcinoma (17 papers, 2017 to 2025). "Among these genes, IL1B, which encodes IL‐1β, has been shown to promote the infiltration of polymorphonuclear MDSCs in renal cell carcinoma." (PMID 37326143, 2023). "Recent data from a renal cell carcinoma animal model evaluating the effect of IL-1β on immune checkpoint inhibitor resistance demonstrated the efficacy of blocking IL-1β in promoting tumor regression." (PMID 36264639, 2022). "In a renal cell carcinoma (RCC) a low level of IL-1β may influence adaptive and innate immune resistance on account of increasing MDSC infiltration." (PMID 35053426, 2022). "The NLRP3 inflammasome, along with IL-18 and IL-1β, plays a significant role in promoting the development of bladder cancer (BC) and renal cell carcinoma (RCC)." (PMID 40718836, 2025). "In renal cell carcinoma (RCC), interleukin (IL)-1β may be a pro-metastatic cytokine." (PMID 31816951, 2019).
Shock (17 papers, 2005 to 2025). The state in which profound and widespread reduction of effective tissue perfusion leads first to reversible, and then if prolonged, to irreversible cellular injury. "IL-1β has a well-established role in autoinflammation, and high levels of IL-1β can lead to symptoms resembling septic shock and multi-organ failure." (PMID 40534851, 2025). "The administration of rTM in the LPS-induced murine septic shock model suppressed the increase in the levels of all cytokines, except IL-1β." (PMID 34066510, 2021). "Moreover, patients with NSTI and septic shock at baseline had significantly higher levels of IL-1β, IL-6, IL-10 and TNF-α level than in patients with NSTI without shock." (PMID 28176831, 2017). "For instance, IL-1β is increased in both human and animal models of sepsis and septic shock and an IL-1 antagonist attenuates the hemodynamic and metabolic manifestations of septic shock." (PMID 25216263, 2014). "Intraperitoneal injection of L. plantarum K8 lysates in LPS-induced endotoxin shock mice alleviated mortality and reduced serum tumor-necrosis factor (TNF)-α, IL-1β, aspartate aminotransferase (AST) and alanine aminotransferase (ALT) levels." (PMID 34072918, 2021). "It was shown that IL-1β, TNF-α, and IFN-γ were below detection limit in patients with septic shock admitted to an ICU." (PMID 28097512, 2017). "We have previously shown that high TPO concentrations in plasma samples from patients with septic shock cooperate with TNF-α and IL-1β in depressing myocardial contractility." (PMID 26963510, 2016). "We documented the early time course evolution of circulatory Prdx1, hypoxic marker carbonic anhydrase IX, inflammatory cytokines including IL-6, IL-8, IL-10, MCP-1, TNF-α, IL-1β, and danger signaling receptors (TLR4 and CD14) in a cohort of cardiogenic shock patients within 1 day after ECMO support." (PMID 27142532, 2016). "Reduced levels of IL-1β, TNF-α and IL-6 were detected in the NLRC4-siRNA group, compared with the sham and NC-siRNA groups (all pCLP vs. NLRC4-siRNA < 0.001; pNC-siRNA vs. NLRC4-siRNA < 0.001), which suggested that NLRC4 gene silencing alleviated the inflammatory reaction induced by septic shock." (PMID 33406504, 2021).
Alcohol (16 papers, 2015 to 2025). "Alcohol-induced hepatotoxicity can cause the nuclear translocation of NF-κB (p65), leading to the transcription of inflammatory genes such as IL-1B, IL-6, and TNFA." (PMID 38681193, 2024). "The two studies also highlighted the vital role of IL-1β in modulating binge-like alcohol consumption and neuropathogenesis associated with alcohol dependence." (PMID 36539796, 2022). "Human genetic studies have shown that polymorphisms in genes encoding receptors for IL-1β may be responsible for a greater susceptibility to develop alcohol dependence." (PMID 35095609, 2021). "Alcohol dependence produced opposite IL-1 effects - enhanced local GABAergic inhibition via a switch in IL-1β signaling to the canonical pro-inflammatory MyD88 pathway." (PMID 37601537, 2023). "A decrease in IL-10 protein abundance was observed after alcohol dependence in male mice, and (low) IL-10 and (high) IL-1β was positively correlated with baseline alcohol intake." (PMID 37601537, 2023). "Activation of the TLR4 pathway, whose end product includes IL-1β, plays an important role in generating the effects of alcohol dependence." (PMID 35095609, 2021). "Alcohol activated the microglia and increased expression of multiple pro-inflammatory cytokines such as tumor necrosis factor α and IL-1β, which may enhance alcohol consumption and contribute to the development of alcoholism." (PMID 36032235, 2022). "The Szabo laboratory found that mice deficient in ASC or in caspase-1 have decreased hepatic and systemic IL-1β levels and showed protection from alcohol-induced liver damage, demonstrating the dependence on the adaptor protein ASC and caspase-1 on the increase of IL-1β in ALD." (PMID 35264978, 2022). "Given that AUDIT‐C contributed substantially to the total AUDIT score in our cohort and that the sample did not display clear evidence of alcohol‐related harm, the strong association between IL‐1β and AUDIT‐C supports its potential as an early‐stage immune marker of hazardous drinking." (PMID 40955775, 2025).
Behçet’s disease (16 papers, 2014 to 2025). "Patients with Behcet’s disease and pyoderma gangrenosum have been reported to harbor somatic mutations in NFKB1 that modulate IL-1β production." (PMID 36355435, 2023). "Upon stimulation with recombinant (r)IL-37, DCs from patients with Behcet’s disease (BD) have decreased IL-6 and IL-1β expression, and increased IL-27 expression." (PMID 29137646, 2017). "Some evidence has also suggested the indispensable role of IL-1β in uveitides involving the whole uveal tract, such as human Behçet's disease and animal EAU." (PMID 26713004, 2015). "Additionally, the activation of the Nlrp3 inflammasome and the maturation of IL-1β have been reported in the autoinflammatory uveitis, such as Behçet’s disease." (PMID 38802924, 2024). "Furthermore, it has been demonstrated that, in comparison to healthy controls, the monocytes from Behçet’s disease patients produce higher levels of IL-1β, IL-6, and TNF-α." (PMID 38674208, 2024). "Notably, preliminary results of an ongoing investigation focused on Behçet's syndrome (BS), a multisystemic inflammatory disorder, shows a similar effect on cytokine IL-1β." (PMID 33204395, 2020). "Moreover, Colchicine, used by the patient for Behçet’s disease, exerts anti-inflammatory effects via inhibition of the NLRP3 inflammasome and IL-1β signalling." (PMID 41025024, 2025).
chronic pancreatitis (16 papers, 2011 to 2025). A chronic inflammatory process causing damage and fibrosis of the pancreatic parenchyma. "In this regard, the administration of AR-42 has been reported to suppress the transcriptional expression of pro-inflammatory cytokines, such as IL-1β, TNFα and IL-6, in trinitrobenzene sulfonic acid-induced chronic pancreatitis in mice." (PMID 37728477, 2023). "Both TGF-β receptor knockout mice and IL-1β over-expression mice consistently develop severe chronic pancreatitis." (PMID 22359633, 2012). "The authors pointed out that the severity of chronic pancreatitis correlated with the expression of IL-1β." (PMID 22133269, 2011). "Moreover, the overexpression of IL-1β induces chronic pancreatitis in mice." (PMID 35183119, 2022). "Taken together, these findings underline the importance of immune activation for chronic inflammation; secondly, the model might be a tool for investigation of carcinogenesis in chronic pancreatitis as older IL-1β transgenic mice display acinar-ductal metaplasia." (PMID 22133269, 2011). "The expression of IL-1β and IL-6 was evaluated by immunohistochemistry on pancreata from patients with PDAC or chronic pancreatitis, or on normal human pancreas." (PMID 39260693, 2024).
diabetic neuropathy (16 papers, 2014 to 2026). A chronic, pathological complication associated with diabetes mellitus, where nerve damages are incurred due to diabetic microvascular injury involving small blood vessels that supply these nerves, resulting in peripheral and/or autonomic nerve dysfunction. "Pro-inflammatory cytokines, including TNF-α, IL-1β, and IL-6, are critical drivers in the development of diabetic neuropathy, but chemokines and anti-inflammatory cytokines also play a substantial role in modulating the disease." (PMID 40149566, 2025). "The ethanolic extract of G. sylvestre reduced the levels of TNF-α, IL-1β, and IL-6 in rats with diabetic neuropathy." (PMID 40006756, 2025). "IL-1β is another critical cytokine that contributes to the inflammatory response in diabetic neuropathy." (PMID 40149566, 2025). "Serum levels of TNF-α, IL-1β, and IL-6 are considerably greater in diabetic neuropathy patients than in healthy people, according to clinical research." (PMID 40149566, 2025). "There was a significant increase in the IL-1β gene expression in the posterior section of the diabetic neuropathy group compared to the healthy control group (P < 0.05)." (PMID 35655729, 2022). "The results showed that JMT reduced the levels of mRNA and NLRP3 protein; also, the expression of IL-1β and caspase-1 in the spinal cord of diabetic neuropathy decreased." (PMID 35655729, 2022). "It reduces the expression of IL-1β and TNF-α, thereby inhibiting the neuroimmune activation of microglia and alleviating the progression of diabetic neuropathy." (PMID 34159207, 2021). "Endurance training reduced the sensitivity of the nervous system to thermal hyperalgesia and mechanical allodynia; also, compared to the diabetic neuropathy group, the gene expressions of NLTP3, P38 MAPK, TNF-α, and IL-1β were significantly reduced by endurance training (P < 0.05)." (PMID 35655729, 2022). "In terms of neuropathic pain, systemic administration of GAS relieved hyperalgesia and allodynia in models of painful diabetic neuropathy and chemotherapy-induced neuropathic pain via inhibition of DRG neuron hyperexcitability, inhibition of microglial activation, or reduction of TNF-α and IL-1β." (PMID 38835032, 2024).
metastatic melanoma (16 papers, 2014 to 2024). A melanoma that has spread from its primary site to another anatomic site. "Numerous studies have demonstrated that NLRP3-inflammasome dysregulation can activate the inflammasome-dependent IL-1β expression in human sporadic metastatic melanoma cells." (PMID 35334544, 2022). "Cultured human metastatic melanoma 1205Lu cells exhibit a time-dependent spontaneous release of IL-1β, which was reduced with NLRP3 silencing using small-interfering RNA (siRNA)." (PMID 33649199, 2021). "Consistently, another study reported that NLRP3 downregulation and reduced IL-1β secretion decreased metastatic melanoma by thymoquinone therapy in a mouse model." (PMID 34747716, 2021). "It has been shown that NLRP3 downregulation and reduced IL-1β secretion decreased metastatic melanoma by thymoquinone therapy in a mouse model." (PMID 34747716, 2021). "The nucleotide-binding domain, leucine-rich containing family, pyrin domain-containing-3 (NLRP3) inflammasome, an intracellular complex that regulates maturation and release of interleukin (IL)-1β, is active in biopsies of metastatic melanoma." (PMID 33649199, 2021). "We found that stimulation of the human metastatic melanoma 1205Lu cells with recombinant IL-1β increased IL-6 after 24 hours compared to the vehicle-treated control cells (p<0.001)." (PMID 34531850, 2021). "In metastatic melanoma cells, IL-1β is released due to the constitutive activation of both NF-κB and NLRP inflammasomes." (PMID 33396632, 2020). "We and others have demonstrated that, in addition to stromal cells, metastatic melanoma cells spontaneously release inflammatory interleukin (IL)-1β, which in turn induces stromal cells to secrete more IL-1β, thus augmenting inflammatory signaling." (PMID 33396632, 2020). "To test the effects of VEM and TRA on IL-1β secretion, we used 1205Lu cells, which carry BRAFV600E mutation and have a relatively high IL1B mRNA expression, as well as IL-1β secretion among human metastatic melanoma cells." (PMID 33396632, 2020). "Human metastatic melanoma samples and human cell lines were described to constituvely express and secrete IL-1β." (PMID 32635472, 2020). "In metastatic melanoma the BRAFV600E mutation was reported to elevate production of IL-1α and IL-1β, abrogated after treatment with VEM." (PMID 29983861, 2018). "In contrast, another key molecule of pyroptosis, ASC, could activate IL-1β secretion and enhance NF-κB activity to promote the growth of metastatic melanoma." (PMID 38334883, 2024). "Other works have demonstrated that ASC is an inhibitor of carcinogenesis by NF-κB transcriptional activity and IκB kinase α/β phosphorylation suppression in primary melanoma, while up-regulated ASC is stimulating the inflammasome, via IL-1β secretion and NF-κB activity, in metastatic melanoma." (PMID 35334544, 2022). "A better understanding of the mechanisms and consequences of IL-1β production by infiltrating macrophages may be of interest for the development of IL-1β targeted therapy, such as anti-IL-1β antibody (canakinumab), against metastatic melanoma." (PMID 28060744, 2017). "However, in metastatic melanoma, the secretion of IL-1β is in autonomous manner, ASC promotes melanomagenesis through enhanced activation of NF-κB pathway." (PMID 28360909, 2017). "Moreover, we evaluated also the effect of SFN/FB on VEGF secretion, since it was proposed that in metastatic melanoma cells the activation of the inflammasome and the consequent IL1-β production may ultimately lead also to the increased production of VEGF." (PMID 32486135, 2020). "Compared to other metastatic melanoma cells, SK-MEL-28 cells secrete extremely low to undetectable levels (<1.9 pg/mL) of IL-1β; however, both VEM- and TRA-resistant SK-MEL-28 cells displayed significantly increased IL-1β secretion." (PMID 33396632, 2020).
metastatic melanoma (continued). "In metastatic melanoma, auto-active IL-1 receptor and other signaling pathways resulted in reduced NF-κB inhibition by ASC in the presence of sustained auto-active inflammasome, leading to spontaneous IL-1β synthesis and release." (PMID 32117971, 2020). "It is speculated that the decreased level of ASC in metastatic melanoma leads to extrinsic competition over limited ASC among different pathways, which results in enhanced inflammasome-dependent secretion of IL-1β and autoactivation of NF-κB pathway." (PMID 28360909, 2017).